ERBB2 (erb-b2 receptor tyrosine kinase 2)
Diseases named in the same sentence as ERBB2 in open-access papers (continued):
Sharing a sentence is not in itself a finding about the gene and the disease.
tumor (continued). "CAR-macrophages, engineered in situ via DNA nanocarriers (such as ErbB2-specific CARs), enhance phagocytic clearance of tumor cells, offering a novel approach particularly effective in brainstem glioma." (PMID 40948940, 2025). "Conversely, CMGT_180321 and its original tumor were consistently classified as luminal A (ERα-, PR+, ErbB2-, and Ki-67 low)." (PMID 40689167, 2025). "By inhibiting the ErbB2-EGFR pathway, lapatinib can effectively suppress the activity of central nervous system atypical teratoid/rhabdoid tumor (CNS ATRT) tumor cells harboring INI1 mutations, both in vitro and in vivo." (PMID 40115023, 2025). "Tumours were grouped into four molecular subtype as in the previous study, including ERBB2+ (ER-, PR-, HER2+), triple negative (ER-, PR-, HER2-), Luminal-A (ER+ and/or PR+, HER2-), and Luminal-B (ER+ and/or PR+, HER2+)." (PMID 40278025, 2025). "In particular, dysregulation of tyrosine kinase receptors, such as epidermal growth factor receptor 1 (ERBB1/EGFR) and epidermal growth factor receptor 2 (ERBB2/ErbB2) activates key signaling pathways involved in tumor cell proliferation and metastasis." (PMID 40689167, 2025). "While the somatic mutational profiles of the patient tumor/PDX-O pairs were largely concordant, we observed a high degree of ERBB2 mutational discordance." (PMID 41422272, 2025). "generated a dual-regulated HSV-1 in which tumor cell-restricted replicative potential was combined with selective transduction via ERBB2 HER-2 receptor retargeting." (PMID 40697381, 2025). "Lapatinib effectively suppresses ERBB2 tyrosine phosphorylation, leading to growth arrest or apoptosis in ERBB2-dependent tumor cell lines." (PMID 41340127, 2025). "This rationale supports artificial reconstruction of the immune synapse by forcibly bridging NKG2D-CAR-engineered NK cells to EGFR/ERBB2-positive tumor cells, thereby overcoming immune escape and addressing intratumoral heterogeneity." (PMID 41209565, 2025). "Further studies with patient derived xenografts models validated that ERBB2 i14e blockage with antisense oligonucleotide enhanced the tumor sensitivity to trastuzumab and its drug conjugates." (PMID 39948369, 2025). "This therapeutic approach targets both the extracellular and intracellular domains of ERBB2, thereby enhancing anti-tumor efficacy." (PMID 40051563, 2025). "Comprehensive ERBB2 (HER2) testing across tumor types is essential to expand access to HER2-targeted therapies." (PMID 40828885, 2025). "A recent phase I neoadjuvant clinical trial based on frontline intratumoral cDC1 immunotherapy demonstrated promising alteration in the TME and induction of tumor regression in ERBB-2+ BC patients." (PMID 40333343, 2025). "The association of Hispanic race and ethnicity with ERBB2-low TNBC remained after adjustment for demographic, socioeconomic, and tumor variables (odds ratio [OR], 0.84; 95% CI, 0.76-0.92; P = .003) (eTable 1 in Supplement 1)." (PMID 40498483, 2025). "Demographic, clinical, and molecular data, including age, gender, race, tumor location, cancer stage, and mutation status (KRAS, NRAS, BRAF, POLE, ERBB-2/HER2, microsatellite status), were collected by reviewing electronic medical records." (PMID 40940860, 2025). "Wild-type CIK cells, administered during the early disease stages, delayed tumor progression in 67% of mice, while ERBB2-CAR CIK cells prevented tumor engraftment in all treated animals." (PMID 40508013, 2025). "These metabolic adaptations correlate with anatomical subtypes (e.g., ERBB2-amplified iCCA vs. PIK3CA-mutant extrahepatic tumours) and influence chemotherapy/targeted therapy efficacy." (PMID 40861435, 2025).
tumor (continued). "In our study, CMGT_071020 was classified as luminal B (ERα-, PR+, ErbB2+, and Ki-67 high), whereas its original tumor was luminal A (ERα+, PR-, ErbB2-, and Ki-67 low)." (PMID 40689167, 2025). "A previous study demonstrated that ERBB2 enhanced tumor cell growth and glycolysis through LDHA upregulation." (PMID 40966256, 2025). "Studies have indicated a correlation between MUC4 expression and the degree of differentiation, tumor stage, and ErbB2 expression in NSCLC." (PMID 40655139, 2025). "GIST enabled more accurate detection of ERBB2 in tumor regions, aiding in the assessment of the functional consequences of the mutation." (PMID 39830364, 2025). "HER2 is a receptor tyrosine-protein kinase that is encoded by the ERBB2 gene on chromosome 17 and plays a key role in tumour biology." (PMID 41463236, 2025). "Afatinib irreversibly inhibits EGFR and ErbB2 tyrosine kinases, reducing tumor cell proliferation, invasion, and metastasis, particularly in tumors with EGFR/ErbB2 overexpression or mutations." (PMID 40281132, 2025). "Strikingly, CD4 and CD8 T cell depletion nearly completely abrogated the inhibitory effect of ERBB2 KO on SCLC tumor growth in immunocompetent mice." (PMID 41361170, 2025). "Conversely, the depletion of AREG receptor ERBB2 in GC cells significantly reduced their tumor sphere formation capacity." (PMID 39950944, 2025). "Studies have shown that dual-targeted CAR-T cells, such as those designed to target both MUC1 and ErbB2, can efficiently eliminate tumor cells expressing either MUC1 or ErbB2." (PMID 40312353, 2025). "Another analysis of the UNITE database identified alterations in ERBB2 and KDM6A, as well as high tumor mutational burden, as biomarkers predictive of better overall survival (OS) in patients who received EV." (PMID 40225697, 2025). "Thereby, they can eliminate a wide range of tumor cell lines originating from various tumor types, with antitumor activity observed in mice bearing xenografts, characterized by ErbB1/2 or ErbB2/3 overexpression." (PMID 40675157, 2025). "In contrast, SCBO-8, SMBO-109, SMBO-114 and SMBO-106 had heterogenous populations of high and low ERBB2 expressing tumor cells." (PMID 41422272, 2025). "Among these, 17 genes were strongly associated with LC, whereas ERBB2, SP1, and ZEB1 were related to other tumor types." (PMID 41226027, 2025). "The adoptive transfer of ERBB2-specific CAR-T cells, which contain a scFv fused to the CD3ζ signaling domain, in BALB/c nude mice demonstrated their ability to recognize and infiltrate ERBB2-expressing tumor cells while slowing tumor growth." (PMID 40771804, 2025). "Taken together, these data show that an ERBB2 inhibition leads to increased T cell-mediated tumor cell killing." (PMID 41361170, 2025). "SMBO-109 was again notable for a heterogeneous population of ERBB2 amplified cells with ~39% of tumor cells having 11 copies of the ERBB2 gene and 55% 17 copies." (PMID 41422272, 2025). "A significant delay (p = 0.0112) in tumor development in Erbb2 mice with Srsf3 KO was observed when compared to Erbb2 mice with WT Srsf3." (PMID 40568073, 2025). "The strategy of dual-targeting, such as combining MUC1 with ErbB2, provides a more refined approach, ensuring effective targeting of tumor cells while sparing normal tissues." (PMID 40312353, 2025). "In summary, we present the diverse landscape of ERBB2/ERBB3 activating alterations and co-alterations across >500,000 solid tumors which has implications for HER2/3-targeted therapies pan-tumor." (PMID 40178042, 2025). "Molecular testing of the tumor tissue at diagnosis revealed ERBB2 gene amplification (estimated copy number of 6) and concurrent FGFR2 amplification (estimated copy number of 128)." (PMID 41357601, 2025).
tumor (continued). "Lapatinib is a 4-anilinoquinazoline kinase inhibitor of the intracellular tyrosine kinase domains of both epidermal growth factor receptor (EGFR [ErbB1]) and of HER2 [ErbB2], which inhibits ErbB-driven tumor cell growth." (PMID 40136358, 2025). "This signature was able to predict HER2‐positive tumours with 95% accuracy (AUC = 0.96) in the cross‐validation set and 83% (AUC = 0.82) in the external test cohort, in comparison to ERBB2 mRNA (AUC = 0.80)." (PMID 40243160, 2025). "By adjusting the threshold of calling amplifications and taking tumor cellularity into consideration, it is possible to increase the sensitivity in detecting ERBB2 amplification to about 80%, while maintaining 100% specificity." (PMID 39682116, 2024). "Amplification of ErbB-2 causes overexpression and hyperactivation of HER2-dependant pathways, therefore stimulating tumour proliferation." (PMID 39273642, 2024). "In the Know Your Tumor study, four ERBB2-amplified patients with PDAC received trastuzumab in combination with various drugs and observed responses ranging from one month to over 12 months." (PMID 38406801, 2024). "ErbB2 amplification showed a high abundance of tumor-infiltrating regulatory T cells and a low abundance of activated NK cells and CD8 + T cells." (PMID 38215117, 2024). "There are 9 targets that involve 5 + malignancy type concurrently, 4 targets with the most repetitions co-exist in 7 tumor types, and ERBB2 is involved in 10 malignancy type." (PMID 39060958, 2024). "In patients with ERBB2/HER2-positive EBC, the association between pCR and EFS differed by tumor intrinsic subtype, and the benefit of dual ERBB2/HER2 blockade was limited to ERBB2-enriched tumors." (PMID 38546612, 2024). "A targeted tumour sequencing test enables comprehensive assessment of alterations in cancer-related genes, including ERBB2." (PMID 38862927, 2024). "We show that the desARE3'UTRERBB2-30 constructs packaged into IO nanocages achieved 50% therapeutic inhibition of the tumor, 80% malignant cell reduction, 50% complete tumor lysis, and 60% complete reduction of ERBB2 IHC." (PMID 38699639, 2024). "Tumours are classified as HER2-positive when more than 10% of cells exhibit an intensity greater than 3+ or 2+ with in situ hybridisation, signifying ERBB2 gene amplification." (PMID 39125873, 2024). "We further observed a significantly higher MDA level in EGFR or ErbB2 overexpressed tumor tissues than vector control tumor tissue upon IKE treatment, suggesting more ferroptosis is induced by IKE treatment in EGFR or ErbB2 overexpressed tumor tissues." (PMID 39604370, 2024). "Cpt1a ablation significantly decreased the basal, ATP synthesis-coupled and maximal oxygen consumption rates (OCR) of ErbB2+ tumor cells, indicating an overall suppression of respiration." (PMID 39097623, 2024). "To further explore mechanisms involved in the altered glucose metabolism of Cpt1a-deficient cells, we first measured glucose uptake and the expression of glucose transporters in wild-type and Cpt1a-null ErbB2-driven tumor cells." (PMID 39097623, 2024). "Lastly, if MET is gained but ERBB2 is lost, the tumor has a greater than 90% chance of being from the small bowel." (PMID 39062773, 2024). "If ERBB2 is gained, the tumor has a 90% chance of being from the pancreas; however, if ERBB2 is lost or normal CCNE1 copy-number status should be assessed." (PMID 39062773, 2024). "Here, we demonstrate that combining Cpt1a inhibition with either the ketogenic diet, rich in LCFAs, or an anti-ErbB2 mAb reduces tumor growth, prolongs survival and enhances anti-tumor immune infiltration." (PMID 39097623, 2024). "used serial circulating tumor (ct)DNA to detect MAPK pathway alterations (SNV or indel in RAS/EGFR/BRAFV600 or MET or ERBB2 amplification) after various therapy lines." (PMID 39080202, 2024).
tumor (continued). "In the more recent Know Your Tumor study, four ERBB2-amplified patients with PDAC received trastuzumab in combination with various drugs and observed responses ranging from one month to over 12 months." (PMID 38406801, 2024). "In gallbladder cancer (GBC), KIF11 facilitated tumor growth via the ERBB2/PI3K/Akt signaling pathway, and the histone acetylation modification (H3K27ac) positively modulated KIF11 expression." (PMID 38433242, 2024). "The majority of tumor cells, characterized by their ErbB2 expression, were located in the inner and border region." (PMID 38203786, 2024). "When analyzed for RNAseq-based tumor intrinsic subtype on the combined cohort, most tumors were ERBB2 enriched (57.9%), followed by luminal B (15.0%), luminal A (9.9%), basal-like (8.8%), and normal-like (8.3%)." (PMID 38546612, 2024). "SDC1 exhibited a greater tumor mutational burden (TMB) score, while ERBB2, KDR, FGF2, KIT, FGFR1, and FGF1 showed lower TMB scores." (PMID 38189813, 2024). "Targeting the ERBB2 pathway with single-agent therapies has shown limited efficacy due to resistance mechanisms and the complexity of gene interactions within the tumor microenvironment." (PMID 39684551, 2024). "The tumor growth was significantly inhibited in the ERBB2 overexpressed group after treating the drug." (PMID 39840049, 2024). "Utilizing RP-182, ErbB2 CAR gene-laden DNA nanocomplex has successfully pinpointed ErbB2-specifc CAR macrophages at the tumor site and directed their phagocytic activity towards tumors." (PMID 39175095, 2024). "The oncogenic mechanisms of HER2, also known as receptor tyrosine protein kinase erbB-2, include promoting tumor cell proliferation, tumor angiogenesis, increasing tumor cell invasiveness, and inhibiting tumor cell apoptosis." (PMID 39247440, 2024). "The different histopathological behaviors of tumours from MMTV‐NCAPHErbB2 double‐transgenic mice prompted us to study molecules from some of the main pathways downstream of ERBB2." (PMID 38344872, 2024). "This targeted approach reduced viable ErbB-2 overexpressing tumor cells in vitro by 96%, highlighting the potential of this delivery strategy to induce tumor cell death." (PMID 39204073, 2024). "Critical genes within the Hallmark Apoptosis pathway, such as ERBB2 (HER2) and CCNA1 are crucial for regulating tumor aggressiveness and responsiveness to therapy." (PMID 39000413, 2024). "Our data clearly indicate that loss of Usp22 strongly impacts Erbb2/Neu RNA and protein expression in MECs isolated from 100-day old MMTV-NIC mice, before the time of the earliest tumor formation, reflecting decreased activity of the MMTV promoter." (PMID 38236941, 2024). "This tumor suppressor miRNA has other targets such as ERBB2, ERBB3 and cytochrome P450 family 24 subfamily A member 1 (CYP24)." (PMID 38954129, 2024). "Significant differences in the prevalence of potentially targetable genomic alterations (ATM, BRAF, BRCA2, ERBB2, IDH1, PIK3CA, and PTEN) were observed in MTAP-loss tumors and varied according to tumor type." (PMID 38330461, 2024). "We observed that high expression of RTKs including EGFR and ErbB2 sensitized cancers to ferroptosis-inducing tumor treatment." (PMID 39604370, 2024). "RT-PCR and in situ hybridization are different methods to evaluate HER2 in tumor material, and some discordant cases were present; for example, some tumors in the low ERBB2 mRNA group had intermediate levels of HER2 amplification group and vice versa." (PMID 38321542, 2024). "In one of these patients, each tumor lineage acquired a genomic alteration in HER2 (ERBB2 amplification, ERBB2L755S mutation), demonstrating convergent evolution of ERBB2 activation following CDK4/6i therapy." (PMID 38503755, 2024). "Together, these findings propose that NCAPH overexpression in ERBB2 tumours engenders more aggressive histopathology, solid tumours with high mitotic indices, and enhanced vascularisation and cell proliferation." (PMID 38344872, 2024).
tumor (continued). "We focused on ERBB2 CN as this variable best represents the total average “dose” of ERBB2 in a tumor and also because it showed slightly superior classification performance." (PMID 38374091, 2024). "The initiating event of the amplicon was due to a break in CDK12; followed by a duplication containing ERBB2 (chr17:37663478-38206775) shared by both BE and tumor, that generated the circular ecDNA through an episomal mechanism." (PMID 38744814, 2024). "Early research has demonstrated that HER-2/ErbB-2 overexpression is linked to a poor prognosis, and the capacity of HER2-specific antibodies to direct HER2 into CBL-dependent endocytosis and degradation pathways is related to their anti-tumor effects." (PMID 39130630, 2024). "With regard to histologic subtypes and their association with ERBB2-low status, we found that tumors that produce mucin (mucinous or mixed mucinous micropapillary) had a lower rate of ERBB2-low expression than the other tumor types combined." (PMID 38517439, 2024). "For most of the patients with serial samples, we can only make educated guesses about why we see fluctuations in the appearance of ERBB2 amplification and/or KRAS activating mutations based on the degree of tumor shed, as detailed above." (PMID 38406801, 2024). "Examples for on-target/off-tumor reactivity are CAR T cells targeting ErbB2/her2, EGFR, and CAIX-specific CAR T cells." (PMID 39594628, 2024). "Our previous F1 backcross (F1Bx) study between the resistant C57BL/6J strain and FVB/N has shown a strong genetic effect on ERBB2-initiated tumour development and metastasis." (PMID 39067134, 2024). "The human epidermal growth factor receptor 2 (HER2), also called ERBB2, is one of the receptors linked to various processes of tumor cells, like growth, cell death, adhesion, movement, and differentiation." (PMID 39409942, 2024). "One triple-proficient patient with an intermediate TMB had amplifications of CCNE1 and ERBB2 in all tumor samples (>20 additional copies), supporting oncogene amplification as a driving mechanism in the absence of DNA damage repair deficiency." (PMID 38175731, 2024). "Given our findings that elevated NCAPH levels correlate with poorer outcomes in luminal ERBB2 tumours in transgenic mice, we identified a gene signature associated with high NCAPH levels." (PMID 38344872, 2024). "Next-generation sequencing (NGS) revealed ERBB2 amplification (CNV=3.50), a high tumor mutation burden (TMB 20.70Muts/Mb), and low microsatellite instability (MSI-L) status." (PMID 39649933, 2024). "Of note, ERBB2 ecDNA was present in both the BE sampled adjacent to the tumor (43B, CN = 7) and EAC (43T, CN = 41, estimated by Hatchet2.027) collected from the same patient at the resection time point." (PMID 38744814, 2024). "Another receptor tyrosine kinase, ERBB2, also known as HER2, has also emerged as a powerful tumor-agnostic molecular signature." (PMID 38920700, 2024). "Like ErbB2, TGF‐β plays a crucial role in cancer development by interacting with ErbB2 to promote tumor progression." (PMID 39479720, 2024). "The results indicate MET, ERBB2, SMAD4, and CCNE1 copy-number status is significantly associated with primary tumor site." (PMID 39062773, 2024). "Previous studies have shown that genetic alterations in the ERBB gene family can aberrantly activate the ERBB1 and ERBB2 signals, leading to tumor initiation, growth, and progression." (PMID 38724606, 2024). "Combined with the results of previous results in this paper, it can be concluded that the C1 SRSF7+ MCs and tumor cells crosstalk through the AREG-EGFR/AREG-(EGFR+ERBB2) signal pathway, thereby exerting a tumor-promoting effect." (PMID 39430754, 2024).